PROS1 (protein S)
Diseases named in the same sentence as PROS1 in open-access papers (continued):
Sharing a sentence is not in itself a finding about the gene and the disease.
tumor (406 papers, 1991 to 2026). "Key interactions between cancer‐associated fibroblasts (CAFs), tumor cells expressing PROS1, and tumor cells expressing MERTK were identified as central drivers of PTMC progression." (PMID 40433916, 2025). "Analysis of scRNA‐Seq data revealed that the TAM signaling ligand PROS1 was specifically expressed in tumor‐associated epithelial cells, CAFs, and endothelial cells in stages II and III." (PMID 40433916, 2025). "Taken together, these findings provide a mechanistic link between BAP1 loss and the suppression of the tumor immune microenvironment in class 2 UMs, and they implicate the PROS1–MERTK pathway as a potential target for immunotherapy in UM." (PMID 35954340, 2022). "PROS1 expression was also closely associated with tumour infiltration by immune cells, especially tumour-associated macrophages, as well as the expression of various immune checkpoint inhibitors, immunomodulators, and immune cell markers." (PMID 35879775, 2022). "As a major vitamin-K-dependent protein in the central nervous system, PROS1 not only plays a vital role in blood coagulation, and some studies have found that it was associated with tumor immune infiltration." (PMID 36685506, 2022). "Following radiation therapy in a colorectal cancer mouse model, MerTK, Protein S and Gas6 are upregulated in tumor associated macrophages." (PMID 31088471, 2019). "Tumors inhibited for PROS1 expression appeared histologically more differentiated, and had downregulated expression of cytokeratins associated with increased tumor cell aggressiveness." (PMID 28118606, 2017). "The tumor-associated macrophages receptor-ligand complex’s PROS1 is a cognate ligand for it." (PMID 40797389, 2025). "Poor clinicopathologic outcomes of PTC, such as extrathyroidal extension, multifocality, larger tumor size, advanced tumor classification, lymph node metastasis, and advanced AJCC tumor, node, metastasis (staging system for cancer) stage, were strongly associated with low PROS1 expression." (PMID 40797389, 2025). "Immunofunctional analyses revealed that PROS1 may be associated with immune checkpoints, T-cell synergistic suppression, T-helper cells, Tfh, Th1 cells, Th2 cells, and tumor-infiltrating lymphocytes (TILs)." (PMID 38613800, 2024). "In addition to GAS6, it is shown that tumor-associated microglia produce protein S which subsequently interacts with and activates AXL in mesenchymal GSCs and promotes growth of GBM cells, and inhibition of AXL suppresses the promoted growth of GBM cells." (PMID 34831142, 2021). "Moreover, we found that PROS1 was strongly correlated with tumor-associated macrophages." (PMID 36685506, 2022). "In vivo subcutaneous implantation also demonstrated that tumors injected with PROS1‐overexpressing K1 cells were significantly larger than those in the NC group, with MERTK knockdown in K1 cells reducing the tumor growth driven by PROS1 overexpression." (PMID 40433916, 2025). "The mechanisms underlying PROS1 activation in adi‐CAFs and MERTK activation in tumor cells were also investigated." (PMID 40433916, 2025). "Considering the critical role of tumor cells in the microenvironment and the dominant contribution of fibroblasts to PROS1 signaling, further principal component analysis (PCA) was conducted on fibroblast populations." (PMID 40433916, 2025). "Conversely, cancer zone B utilized Sema4a/d-Plxnb2 and Pros1-Axl interactions to coordinate crosstalk within cancer_macro 1 populations, driving immune evasion and promoting tumor invasion and metastasis." (PMID 40723284, 2025). "Subsequently, experimental validation confirmed that MICA+ tumor cells upregulated MMP9 expression in macrophages through the PROS1-AXL axis." (PMID 38254761, 2024). "Eric Ubil initiated a macrophage study and determined that tumor cells express MERTK ligands, GAS6, and Protein S, providing a source of tumor microenvironment (TME) ligand." (PMID 39062902, 2024).
tumor (continued). "Tumour suppression by protein S-palmitoylation can be achieved by promoting the activation of tumour suppressor signalling pathways or blocking the activation of oncogene signalling pathways." (PMID 38485938, 2024). "MICA+ tumor cells stimulated the secretion of MMP9 from macrophages through the PROS1-AXL axis, thereby facilitating the proteolytic shedding of MICA into soluble MICA." (PMID 38254761, 2024). "In B16/F10 melanoma, GAS6 expression increased with tumor growth in vivo while Protein S was expressed at a high level from the onset." (PMID 39062902, 2024). "Less is known about the control of GAS6 and PROS1 although both have been observed in the tumor microenvironment released from both tumor cells and infiltrating immune cells." (PMID 38906855, 2024). "When co-cultured in transwell assay with peritoneal mouse macrophages, the tumor cell secreted PROS1-suppressed inflammatory cytokine transcription induced by a 24-h LPS/IFN-γ treatment of the peritoneal macrophages." (PMID 39062902, 2024). "When PROS1 is overexpressed in FMRP‐KO cancer cells, the upregulation of PROS1 promotes tumor growth and reduces the expression of CD86 in TAM." (PMID 36968189, 2023). "Subsequently, the relationship between PROS1 expression with immune infiltration and tumor immune microenvironment was analyzed in detail." (PMID 36685506, 2022). "PROS1 plays a vital pathogenic role in the immuno-oncological context of the TME, affects the infiltration of tumour tissue by immune cells, and influences patient prognosis." (PMID 35879775, 2022). "Protein S (PROS1) is a recognized ligand of the Tyro3, AXL, and Mer (TAM) family of tyrosine kinases receptors, it was secreted by activated T cells or tumor-associated macrophages." (PMID 36685506, 2022). "As for PROS1 (protein s), one of its roles is to inhibit tumor metastasis by mediating inflammation and immunization." (PMID 35281834, 2022). "To analyse the possible influence of PROS1 expression on the tumour microenvironment during tumour development, we analysed immune and stromal scores of LGG samples using the R package “Estimate”." (PMID 35879775, 2022). "As shown in the forest plot, we first analysed the correlation between PROS1 expression and overall survival in 33 tumours from the TCGA database." (PMID 35879775, 2022). "The specific mechanism of PROS1 in promoting tumor progression and immune-suppressive should be further explored in future studies." (PMID 36685506, 2022). "At the protein level, immunohistochemistry stainings were used to investigate the PROS1 expression in 15 paired tumour samples compared with adjacent normal tissues." (PMID 35879775, 2022). "At the same time, it is worth noting that the TAM receptor and their two ligands, GAS6/ PROS1, have been reported to abnormally express in various tumor microenvironments or promote tumor growth and infiltration." (PMID 35033201, 2022). "Phosphatidylserine (PtdSer) is a major coregulator of the TAM signaling pathway, binding PROS1 or GAS6 ligands, and is implicated in tumour immunity and inflammation." (PMID 36203174, 2022). "Pros1 knockout tumor-bearing mice showed an increase in innate and adaptive immune responses and significantly prolonged survival." (PMID 33391402, 2021). "It has been found that tumor cells can secrete protein S (Pros1), a Mer/Tyro3 ligand, to suppress M1 polarization and lower anti-tumor immune response." (PMID 33224886, 2020). "Taken together, these results suggest that myeloid cells represent a constitutive source of Gas6 and PROS1 in the tumor microenvironment." (PMID 33101282, 2020). "We have shown that low doses of PROS1 favor the tumor cells, by co-culturing MERTK-expressing T cells with high MERTK-expressing cancer cells." (PMID 31664482, 2020). "The TAM receptors are a family of receptor tyrosine kinases with shared ligands Gas6 and Protein S that skew macrophage polarization towards a pro-tumor M2-like phenotype." (PMID 31088471, 2019).
tumor (continued). "In conclusion, we have shown that ProS1 is a tumour-derived functional ligand for Tyro3 that supports cancer cell survival." (PMID 31766614, 2019). "Tumor-secreted PROS1 modulates host macrophages by shifting them towards the M2-like tissue repair phenotype, facilitating cancer progression." (PMID 31775787, 2019). "GAS6 and PROS1 were both found to be expressed by tumor cells, and led to autocrine activation of the receptors, promoting oncogenic characteristics." (PMID 31775787, 2019). "Studies reveal that, compared to normal cells, tumor cells rely more on cap-dependent protein synthesis and synthesis of oncogenic proteins." (PMID 30286779, 2018). "In-vivo, PROS1 inhibition decreased tumor growth and decreased tumor cell differentiation in a xenograft model." (PMID 28118606, 2017). "Inhibition of PROS1 expression suppressed tumor cell proliferation, migration and anchorage-independent growth in-vitro." (PMID 28118606, 2017). "Taken together, we identify PROS1 as a driver of OSCC tumor growth and a modulator of AXL expression." (PMID 28118606, 2017). "To allow further molecular identification and quantification of the tumor cells as a function of PROS1 expression, we assessed the expression levels of cytokeratins (CK) 5/6, 8/18 and 19 by immunohistochemical analysis." (PMID 28118606, 2017). "PROS1 immunoreactivity was observed in shEV in the basal and intermediate cell layers, with a strong signal in the basal cells surrounding the tumor nest structures characteristic of OSCC." (PMID 28118606, 2017). "We verified PROS1 expression in shEV tumors, as well as conservation of PROS1 knockdown in shPS1 and shPS2 tumors during in-vivo growth by immunohistochemistry of tumor sections at the endpoint." (PMID 28118606, 2017). "The marked reduction in cytokeratin levels following PROS1 knockdown supports the pathological assessment, and together with reduced tumor growth in-vivo indicate decreased malignancy of OSCC tumors following PROS1 knockdown." (PMID 28118606, 2017). "Our data suggest an additional role of Protein S in tumor progression, beside its well known function in the coagulation process, that should be studied in more detail in the future." (PMID 27486820, 2016). "The interaction of PS with the overexpressed TAMs via its ligands, Gas6 and Pros1, on the tumor cells induce several tumorigenic phenotypes including tumor cell survival, proliferation, chemoresistance as well as tumor metastasis." (PMID 27916840, 2016). "While the discussion above has focused mainly on the up-regulation of TAMs and TAM ligands (Gas6/Pros1) in the tumor microenvironment, a final important factor, namely the concomitant dysregulation of PS in the tumor microenvironment also warrants mention." (PMID 27916840, 2016). "These efforts are based on recent observations that in the tumor microenvironment, both over-expression of TAMs and its ligands (Gas6 or Pros1) occur concomitantly." (PMID 27916840, 2016). "Gas6, protein S and galectin-3, the ligands for Mer, have been also described to be frequently overexpressed in tumor tissues of NSCLC, suggesting that Mer receptor is continuously activated in NSCLC via autocrine and/or paracrine mechanisms." (PMID 25826078, 2015). "However, MERTK knockdown in sh‐PROS1 K1 cells reduced the tumor growth induced by PROS1‐overexpressing CAFs." (PMID 40433916, 2025). "Rothlin and co-workers had previously demonstrated that TAM RTKs inhibit TLR agonists and the lab tested whether TLR activity can augment PROS1 deletion in the tumor cell." (PMID 39062902, 2024). "Moreover, scRNA-seq analyses revealed a significant increase in PROS1 expression in HCC tumor cells exhibiting positive expression of IRF1 or MICA." (PMID 38254761, 2024).
tumor (continued). "To further validate the involvement of the PROS1-AXL axis in the upregulation of macrophage MMP9 via MICA+ tumor cells, we introduced the AXL inhibitor cabozantinib to macrophages stimulated via recombinant human PROS1 protein and co-cultured with IRF1+ Huh7 cells." (PMID 38254761, 2024). "In addition, some studies revealed the effects of PROS1 expression on the tumor immunosuppressive microenvironment." (PMID 36685506, 2022). "As many cancer types express MERTK and TYRO3 as well as their ligand PROS1, we hypothesized that tumor cells may exploit the TAM-receptor-dependent regulation of osteoblasts and inhibit their function via MERTK39–45." (PMID 36509738, 2022). "Tumour-secreted PROS1 can decrease the expression of macrophage M1 cytokines in vitro and in vivo." (PMID 35879775, 2022). "Second, the possible mechanisms of DNMTs, MMRs, DNA methylation, alternative splicing, the identified lncRNA-TF-gene triplet and the roles of PROS1 in tumour migration, immune cell infiltration, and tumour escape should be explored in more detail in future studies." (PMID 35879775, 2022). "Tumor immune estimation resource (TIMER) and spearman correlation analysis were applied to evaluate the associations between infiltration levels of immune cells and the expression of PROS1." (PMID 36685506, 2022). "PROS1 not only plays an important role in the blood coagulation system, and recent studies have found that it was correlated with the development of tumors, especially related to tumor immune infiltration." (PMID 35879775, 2022). "Because lncRNAs and TFs have been widely found to play indispensable roles in the occurrence and progression of tumours, the LncMAP database was used to explore TFs and lncRNAs that may regulate PROS1 expression in LGG." (PMID 35879775, 2022). "Mutational inactivation of BAP1 in UM may lead to a suppressive TIME at least in part by upregulation of PROS1 in tumor cells and phospho-activation of MERTK in tumor-associated macrophages." (PMID 35954340, 2022). "Additionally, the correlations of PROS1 expression with multi-omic data and tumour infiltration by immune cells in LGG remain undetermined." (PMID 35879775, 2022). "Both of these results demonstrated that, in addition to increasing immune cell infiltration, high PROS1 expression could also induce macrophage M2 polarization that may induce tumor." (PMID 36685506, 2022). "The study shows that the Pros1 / TAM interaction may be a new strategy for tumor-mediated immunosuppression." (PMID 33391402, 2021). "In addition, MERTK-activation by exogenous PROS1 supplementation increased cytotoxicity of tumor infiltrating lymphocytes against autologous melanoma cells, despite high level of MERTK expression by the autologous tumor cell line." (PMID 31664482, 2020). "ROC curves indicated that RP11-328K4.1, hsa-miR-27a-3p and PROS1 exhibited great diagnostic efficiency in ICC tumor tissues and nontumor tissues." (PMID 31956102, 2020). "Gas6 and Pros1 are ubiquitously produced by in vitro derived myeloid cells, suggesting that they could be a source of ligands within the tumor microenvironment." (PMID 33101282, 2020). "Recently, it was demonstrated that tumor cells-secreted PROS1 could inhibit M1 polarization in mouse models and thus reduced anti-tumor immune response." (PMID 33101282, 2020). "However, relatively little is currently known about the role of ProS1 as a TAM ligand for tumours, with a few studies so far having reported ProS1 overexpression in different cancers." (PMID 31766614, 2019). "Since tumor cells secrete the ligands PROS1 and GAS6, it is hypothesized that they too contribute to this immune suppressive phenotype." (PMID 31775787, 2019). "Furthermore, cancer cell-derived ProS1 is a functional activator of Tyro3 and hence can be an autocrine or paracrine supporter of tumour progression." (PMID 31766614, 2019).
tumor (continued). "The role of PROS1 in immune cells and its impact on tumor progression and metastasis is still unknown, and is currently a subject of active research in our lab." (PMID 31775787, 2019). "In addition, by contrast, some studies have shown inhibitory effects of Gas6/ProS1 on tumour growth through inhibition of angiogenesis." (PMID 31766614, 2019). "Moreover, they have clearly identified ProS1 as a tumour-derived, activating ligand of Tyro3 beyond its role in blood coagulation regulation." (PMID 31766614, 2019). "The present study directly compared both TAM ligands as Tyro3 ligands in native Tyro3-expressing human cancer cell lines, the biological functionality of tumour secreted ProS1, and the diversifying capability of Tyro3 in terms of coupling to intracellular signalling." (PMID 31766614, 2019). "Thus, tumor cells produce PROS1 in response to pro-inflammatory M1 cytokines and PROS1 stimulates TYRO3 and MERTK on macrophages to promote an anti-inflammatory M2 phenotype, thereby repressing the innate immune response in the tumor microenvironment." (PMID 30501104, 2018). "Having established that apoptotic and calcium-mediated stressed cells, via externalized PS, could act as cell-based ligands to activate TAMs in the presence of Gas6/Pros1, we next explored whether PS-positive tumor exosomes could also activate TAMs." (PMID 29176978, 2017). "Moreover, PROS1 knockdown reduced anchorage-independent growth in-vitro, reduced tumor xenograft growth in nude mice and altered their differentiation profile." (PMID 28118606, 2017). "At 7 weeks post implantation PROS1 knockdown tumors had significantly smaller tumor volumes with 66% smaller tumors for shPS1 cells (27 mm3 mean tumor volume, P < 0.03), and 96.2% smaller tumors for shPS2 (3 mm3 mean tumor volume, P < 0.001), compared to shEV (78 mm3 mean tumor volume)." (PMID 28118606, 2017). "Accordingly, compared to control-treated cells, PROS1 knockdown cells appeared histologically more differentiated, and correlated with a reduction in cytokeratin markers CK5/6, CK8/18 and CK19 associated with increased dysplasia and tumor aggressiveness." (PMID 28118606, 2017). "Notably, PROS1 expression in fibroblasts strongly overlaps with adi‐CAFs, suggesting that adi‐CAFs may contribute to tumor progression through PROS1 secretion." (PMID 40433916, 2025). "Immune cell infiltration and tumour microenvironment, immune checkpoint inhibitors, immunomodulators, immune cell markers, and therapeutic outcomes in clinical studies of immune checkpoint blockade were subsequently explored, and we identified significant correlations with PROS1 expression." (PMID 35879775, 2022). "According to analyses of the Tumor Immune Estimation Resource (TIMER) database, six types of immune cells (B cells, CD8 + T cells, CD4 + T cells, macrophages, neutrophils, and dendritic cells) were associated with PROS1 expression and prognosis in patients with LGG." (PMID 35879775, 2022). "We additionally analysed PROS1 expression in 31 types of tissues using the GTEx dataset, determined its expression in 21 tumour cell lines using the Cancer Cell Line Encyclopedia database, and compared the expression between tumour and normal tissues using The Cancer Genome Atlas (TCGA) database." (PMID 35879775, 2022). "Furthermore, the ProS1-Tyro3 interaction is primarily coupled to Erk signalling although it displays signalling diversity dependent upon its representative expression as a TAM receptor in tumour cells." (PMID 31766614, 2019). "Furthermore, knockdown of PROS1 reduced tumor growth in a xenograft transplantation model." (PMID 28118606, 2017). "Collectively, these findings suggest that PROS1 is a potential prognostic biomarker and molecular regulator in PDAC and thus support further investigation into the dual role of PS in tumor progression." (PMID 41977152, 2026).